CDC25A (cell division cycle 25A)
Diseases named in the same sentence as CDC25A in open-access papers (continued):
Sharing a sentence is not in itself a finding about the gene and the disease.
breast tumor (4 papers, 2012 to 2020). "Moreover, DLL1 downregulation caused a 2-fold reduction in the expression levels of CDC25A and SKP2 genes, which are often overexpressed in breast tumors and involved in BC pathogenesis." (PMID 31107884, 2019). "We next examined the correlation between BRE and CDC25A levels in BRCA2 mutant human breast tumors." (PMID 29416040, 2018). "Furthermore, we confirmed a positive correlation between BRE and CDC25A levels in human breast tumors." (PMID 29416040, 2018). "Other genes have been correlated with tumorigenesis, such as CDC25A, PTPN11, and IL8, but have not been extensively studied in regard to migration and invasion of breast tumor cells." (PMID 23113900, 2012).
endometrial cancer (4 papers, 2011 to 2020). Primary or metastatic malignant neoplasm involving the endometrium (mucous membrane that lines the endometrial cavity). "Survival analysis showed that the higher the expression levels of lncRNAs C2orf48, PSAT1, KIF23, CCNE1, CDC25A and CBX2 in patients with endometrial cancer, the poorer the prognosis." (PMID 30581678, 2018). "Two genes (CDC25A and IGF1R) were up-regulated (p = 0.04) in endometrial carcinoma, and CPEB1 was down-regulated (p = 0.05)." (PMID 27271671, 2016).
squamous cell carcinoma (4 papers, 2001 to 2023). A carcinoma arising from squamous epithelial cells. "The upregulation of CDC25A expression would lead to the growth of tumor in squamous cell carcinoma." (PMID 35016691, 2022). "CDC25A but not CDC25B may be a new prognostic factor for squamous cell carcinoma of the oesophagus." (PMID 11487274, 2001).
adenoma (3 papers, 2002 to 2024). A neoplasm arising from the epithelium. "USP8-mutated adenomas showed higher level of POMC, CDC25A, MAPK4 but lower level of CCND2, CDK6, CDKN1B than USP8-wild-type tumors." (PMID 38862897, 2024). "According to our findings, cdc25A was frequently overexpressed in all types of thyroid neoplasms including benign adenoma arising from follicular cells." (PMID 12085185, 2002).
Alzheimer disease (3 papers, 2008 to 2024). A progressive, neurodegenerative disease characterized by loss of function and death of nerve cells in several areas of the brain leading to loss of cognitive function such as memory and language. "Conversely, for hub genes identified from upregulated DEGs, Alzheimer’s disease has been linked to CD2, CDC25A, CKS2, LCK, PRKACG, and S100A7." (PMID 39766348, 2024). "Cdc25a activity is increased in degenerating neurons of patients who died with Alzheimer's disease." (PMID 22348126, 2012).
COVID-19 (3 papers, 2021 to 2024). A disease caused by infection with severe acute respiratory syndrome coronavirus 2. "In COVID-19, CDC25A has been found to be closely associated with immune cell infiltration such as plasma cells, macrophages, T cells, dendritic cells and NK cells, and plays an important role in disease progression as a biomarker for COVID-19 diagnosis." (PMID 38978778, 2024). "Four of these genes (ACE, KLF5, IDO1, and CDC25A) have been reported to be associated with the pathological mechanisms of COVID-19 and sarcopenia." (PMID 38978778, 2024). "ACE (AUC: 0.923), CYP1A1 (AUC: 0.902), EME1 (AUC: 0.977), CD52 (AUC: 0.970), MYBL2 (AUC: 0.995), CDC25A (AUC: 0.998), BCL6 (AUC: 0.966) and CD3D (AUC: 0.955) showed relatively good diagnostic efficiency in distinguishing COVID-19 patients from healthy controls." (PMID 38978778, 2024). "CDC25A, GUSB, MYBL2, and SDAD1 were identified as key genes in severe COVID-19." (PMID 35887528, 2022).
diabetes (3 papers, 2019 to 2023). "In ECs, MiR-503 directly downregulates CCNE1 and cdc25A in a situation mimicking ischemia and diabetes (high glucose/low growth factors)." (PMID 31035988, 2019). "Furthermore, the PPN-delivered miR-503 inhibitor effectively modulates endothelial cell expression of miR-503 and its downstream targets, CCNE1 and CDC25a, thereby enhancing endothelial angiogenesis in diabetes-like conditions as demonstrated by tubulogenesis and migration in vitro." (PMID 37630945, 2023).
infertile (3 papers, 2018 to 2024). "In reproduction, CDC25A plays a crucial role in spermatogenesis, where its decreased expression is linked to infertility and failed sperm retrieval." (PMID 39981136, 2024). "Therefore, low CDC25A expression in infertility may be caused by mutations/polymorphisms that affect the family of DAZ, E2F-1 and c-myc genes in the metabolic cascade or other factors that interfere with mRNA production or stability." (PMID 30009144, 2018). "As early as 2006, a group found that CDC25A was down-regulated in the testis tissue of male infertile patients." (PMID 32029690, 2020). "This study examined the levels of mRNA and protein CDC25A in testicular tissue of infertile men using qPCR and immunohistochemistry, respectively." (PMID 30009144, 2018).
myeloma (3 papers, 2018 to 2024). "Moreover, RRM2 and CDC25A are among a 37 gene product signature for responsiveness to rapamycin and entinostat in myeloma and thereby prognostic of risk and survival." (PMID 38509117, 2024).
skin cancer (3 papers, 2020 to 2023). "In order to develop a strategy for targeting CDC25A binding to 14-3-3ε, we first needed to determine which 14-3-3 isoforms are expressed in skin cancer and also associate with CDC25A in skin cancer cells." (PMID 32934772, 2020). "However, whether 14-3-3ε associates with CDC25A in skin cancer cells, and what effect targeting this interaction may have on SCC cell viability has not been previously reported." (PMID 32934772, 2020). "Moreover, it was reported that the interaction of CDC25A with 14–3-3ξ inhibits cell-cycle progression in HeLa and skin cancer cells." (PMID 35142956, 2023). "From these data and our published work we hypothesized that interfering with 14-3-3ε binding to CDC25A would be a useful strategy for killing skin cancer cells." (PMID 32934772, 2020). "We hypothesized that targeting CDC25A-14-3-3ε interactions may be an effective strategy for inducing skin cancer cell apoptosis." (PMID 32934772, 2020). "More work is needed to determine the effect of CDC25A on Raf-1 phosphorylation and how Raf-1 may impact Akt activation in skin cancer." (PMID 32934772, 2020). "Understanding how CDC25A can regulate 14-3-3ε expression, whether it can affect the expression of other 14-3-3 isoforms, and how this affects the skin’s response to UV-induced DNA damage and tumorigenesis may provide more insight into the role of CDC25A and 14-3-3ε in skin cancer development." (PMID 32934772, 2020). "Mouse skin and skin tumors lacking CDC25A expression show decreased levels of 14-3-3ε protein and 14-3-3ε transcripts compared to wild type skin and tumors (not shown)." (PMID 32934772, 2020).
triple-negative breast carcinoma (3 papers, 2021 to 2025). An invasive breast carcinoma which is negative for expression of estrogen receptor (ER), progesterone receptor (PR), and human epidermal growth factor receptor 2 (HER2). "The CDC25A gene regulates the G1/S and G2/M checkpoints of the cell cycle, and its dysregulation has been implemented in the development of triple-negative breast cancer." (PMID 37374977, 2023). "For instance, Cdc25A was upregulated in triple-negative breast cancer (TNBC), and a Cdc25A inhibitor suppressed TNBC growth." (PMID 34743185, 2021). "In triple-negative breast cancer models, KLT effectively blocked cell cycle progression at the G2/M phase by downregulating CDK1, CDK2, and CHEK1, inhibiting CDC25A, CDC25B, MELK, and AURKA activity, suppressing mitosis, and inducing apoptosis." (PMID 41164166, 2025).
bone sarcoma (2 papers, 2014 to 2015). A sarcoma that arises from the bone. "Therefore, the inhibition of proliferation induced by dnTCF4 or siLEF1 in bone sarcoma cells in the present study might be mediated through c-Myc as well as CDC25A." (PMID 25999350, 2015). "We did observe that increased expression of ANGPT2 and CDC25A was maintained throughout culture passages; however, these genes are not correlated with bone sarcoma etiology." (PMID 24716831, 2014). "ANGPT2 and CDC25A maintain higher expression levels during in vitro culture in MSC-SAR compared to MSC-CTRL, but expression of these genes has not been correlated with bone sarcoma etiology." (PMID 24716831, 2014).
chronic myeloid leukemia (2 papers, 2022 to 2025). "This exploratory study identifies a potential inverse association between miR-122-5p and CDC25A expression in chronic myeloid leukemia." (PMID 41373559, 2025). "This study integrates bioinformatics analysis with in vitro RT-qPCR validation in K562 chronic myeloid leukemia cells to explore the potential regulatory relationship between miR-122-5p and CDC25A." (PMID 41373559, 2025).
Chronic Myeloproliferative Disorder (2 papers, 2015 to 2025). "CDC25A is also constitutively expressed downstream of oncogenic tyrosine kinases, including NPM-ALK and BCR-ABL, as well as JAK2 V617F in myeloproliferative neoplasms." (PMID 26515730, 2015).
cutaneous squamous cell carcinoma (2 papers, 2020). "We previously documented an anti-apoptotic role for CDC25A in cutaneous squamous cell carcinoma (SCC), an activity dependent on its association with 14-3-3 proteins." (PMID 32934772, 2020).
dysplasia (2 papers, 2018 to 2021). A usually neoplastic transformation of the cell, associated with altered architectural tissue patterns. "In contrast, LIMD1 and CDC25A showed high nuclear expressions in both basal/parabasal (80.06%, 82.76% respectively) and spinous layers (80.06%, 74.71%) of normal epithelium with significant loss of their expression during development of dysplasia (63.88%, 52.78%) and HNSCC (43.42%, 47.37%)." (PMID 29672635, 2018).
esophageal cancer (2 papers, 2020 to 2024). A primary or metastatic malignant neoplasm involving the esophagus. "Accordingly, ART caused a G0/G1 phase arrest in vitro and in vivo in esophageal cancer by down-regulating CDC25A, a CDK2 activator, thereby compromising entry into the S phase." (PMID 33316936, 2020).
fibrosarcoma (2 papers, 2020 to 2023). A malignant mesenchymal fibroblastic neoplasm affecting the soft tissue and bone. "For example, in liposarcoma, leiomyosarcoma, synovial sarcoma, and fibrosarcoma, the Wnt/β-catenin signaling pathway is known to be constitutively activated, leading to enhanced proliferation and viability, with CDC25A identified as a key target gene." (PMID 38264665, 2023). "Fibrosarcoma HT-1080 and leiomyosarcoma CP0024 and SK-UT-1 cells were transiently transfected with CDC25A siRNA, and cell viability was continuously monitored using the xCELLigence system." (PMID 32911761, 2020).
head and neck cancer (2 papers, 2007 to 2020). A primary or metastatic malignant neoplasm affecting the head and neck. "Recently, overexpression of cdc25A was found in many breast, head and neck cancers." (PMID 19458769, 2007).
ischemia (2 papers, 2012 to 2019). A hypoperfusion of the BLOOD through an organ or tissue caused by a PATHOLOGIC CONSTRICTION or obstruction of its BLOOD VESSELS, or an absence of BLOOD CIRCULATION. "UCP2 decreases the levels of Cdc25a, therefore it may reduce apoptotic cell death induced by ischemia." (PMID 22348126, 2012).
leiomyosarcoma (2 papers, 2020 to 2023). An uncommon, aggressive malignant smooth muscle neoplasm, usually occurring in post-menopausal women. "Conversely, in leiomyosarcoma SK-UT-1 cells, one of the most resistant cell lines to this Wnt inhibitor, the CDC25A expression was greater in the nucleus than in the cytoplasm." (PMID 32911761, 2020). "In agreement with their sensibility to PRI-724, the greatest inhibitory effect of this compound on CDC25A protein levels was observed in liposarcoma 93T449 cells when compared with leiomyosarcoma CP0024 or SK-UT-1 cells." (PMID 32911761, 2020). "Liposarcoma 93T449 and leiomyosarcoma CP0024 cells, which were more sensitive to disruption of CBP/β-catenin interaction, had higher levels of CDC25A protein in the cytoplasm than in the nuclei." (PMID 32911761, 2020).
leukaemia (2 papers, 2021 to 2025). "The PVCA suggested that CDC25A gene expression accounts for 28.4% of gene expression profile variances between the samples, while the type of diagnosed leukemia accounts for 7% of the variance." (PMID 41373559, 2025). "The PVCA showed that CDC25A gene expression accounts for 35.3% of gene expression profile variances between the samples, while the type of diagnosed leukemia accounts for 13% of the variance." (PMID 41373559, 2025). "Even though RAF is not significantly differentially expressed in the leukaemia signature itself, it is the first neighbour of significantly differentially expressed genes of the disease, such as PBK, OIP5 and CDC25A, and may thereby exert indirect effects on the system." (PMID 34131166, 2021).
non-Hodgkin lymphoma (2 papers, 2023 to 2025). Distinct from Hodgkin lymphoma both morphologically and biologically, non-Hodgkin lymphoma (NHL) is characterized by the absence of Reed-Sternberg cells, can occur at any age, and usually presents as a localized or generalized lymphadenopathy associated with fever and weight loss. "Due to its proto-oncogenic properties, overexpression of CDC25A has been observed in various malignancies, including Non-Hodgkin Lymphoma and esophageal, gastric, lung, thyroid, head, and neck cancers." (PMID 41373559, 2025).
osteosarcoma (2 papers, 2014 to 2016). A usually aggressive malignant bone-forming mesenchymal neoplasm, predominantly affecting adolescents and young adults. "Both miR-449a and miR-449b were first described as tumor suppressors in osteosarcoma cells, targeting CDK6 and CDC25A." (PMID 26934316, 2016).
polycystic kidney disease (2 papers, 2013 to 2024). A usually autosomal dominant and less frequently autosomal recessive genetic disorder characterized by the presence of numerous cysts in the kidneys leading to end-stage renal failure. "In polycystic kidney disease the downregulation of miR-15a is thought to contribute to in vitro cystogenesis by targeting the cell cycle regulator Cdc25A." (PMID 23424003, 2013).
atherosclerosis (1 paper, 2025). A disease characterized by the build-up of fatty material and calcium deposition in the arterial wall resulting in partial or complete occlusion of the arterial lumen. "Subsequent functional annotation identified eight atherosclerosis-relevant candidate genes: transcription factors (KLF12, KLF6, KLF9, and MEF2C), epigenetic regulators (HDAC9), and signaling molecules (YAP1, SOCS6, and CDC25A)." (PMID 41373654, 2025).
Cerebral ischemia (1 paper, 2018). Restriction of arterial blood supply to the brain associated with insufficient oxygenation to support the metabolic requirements of the tissue. "We previously showed that exogenous overexpression of miR-424 in the brain protects against permanent focal cerebral ischemia injury via suppression of microglia-mediated inflammatory response by reducing the expression of cell cycle proteins CDK6, cyclin D1, CDC25A." (PMID 29675290, 2018).
cervical squamous cell carcinoma (1 paper, 2023). A squamous cell carcinoma arising from the cervical epithelium. "ALX3 is a member of the homeobox family with oncogenic potential in cervical squamous cell carcinoma through the transactivation of CDC25A by recruiting lysine demethylase 2B." (PMID 37760434, 2023).
clear cell carcinoma (1 paper, 2019). "Among the downregulated genes CDC25A (−1.67-fold) was downregulated only in clear cell carcinoma but not in other two subtypes." (PMID 30863721, 2019).
colorectal tumors (1 paper, 2022). "For instance, DYRK2 expression was significantly down-regulated in colorectal tumors whereas CDC25A showed increased expression in comparison with healthy tissue; similarly, DYRK2 expression was higher in kidney tumors than in adjacent normal tissues whereas CDC25A showed the opposite pattern." (PMID 34363019, 2022).
diabetic nephropathy (1 paper, 2025). "The downregulation of CDC25A, E2F3, and NFIB increases the risk of developing diabetic nephropathy." (PMID 40041782, 2025).
endothelial dysfunction (1 paper, 2022). In vascular diseases, endothelial dysfunction is a systemic pathological state of the endothelium (the inner lining of blood vessels) and can be broadly defined as an imbalance between vasodilating and vasoconstricting substances produced by (or acting on) the endothelium. "In conclusion, we successfully identified three “real” hub genes (VEGFA, CDC25A, and LOX), and six crucial miRNAs (hsa-mir-24-3p, hsa-mir-124-3p, hsa-mir-195-5p, hsa-mir-146a-5p, hsa-mir-155-5p, and hsa-mir-23b-3p) associated with endothelial dysfunction in HPH based on bioinformatic analysis." (PMID 36483920, 2022).
Ewing sarcoma (1 paper, 2019). A small round cell tumor that lacks morphologic, immunohistochemical, and electron microscopic evidence of neuroectodermal differentiation. "In this study, we showed that APCDD1 knockdown increased the expression of CDC25A, LRP6, LEF1 and NKD1, which are confirmed targets of the canonical Wnt pathway in Ewing sarcoma, implying that APCDD1 might act as a Wnt inhibitor in this cancer." (PMID 30496486, 2019).
Hepatic cysts (1 paper, 2020). "An increase in CDC25A protein due to alleviation of miRNA-mediated repression exacerbates hepatic cyst formation and colon cancer." (PMID 31911652, 2020).
medulloblastoma (1 paper, 2024). A malignant, invasive embryonal neoplasm arising from the cerebellum. "For example, netropsin reduced the expression of cdc25A by suppressing its promoter activity and inhibited intracranial medulloblastoma cell growth both in vitro and in vivo." (PMID 39020380, 2024).
meningioma (1 paper, 2018). A generally slow growing tumor attached to the dura mater.
metastasis (1 paper, 2001). The spread or migration of cancer cells from one part of the body (where they first appeared) to another. "CDC25A (+), as well as CDC25B (+), was more frequently found in patients with deeper tumour invasion and lymph node metastasis, while tumour size was correlated only with CDC25A expression." (PMID 11487274, 2001).
myeloid neoplasm (1 paper, 2025). Proliferation of myeloid cells originating from a primitive stem cell. "Although transcriptomic validation utilized predominantly Philadelphia-negative myeloproliferative samples, these analyses were designed to identify conserved CDC25A-associated signatures within myeloid neoplasms." (PMID 41373559, 2025).
ovarian tumor (1 paper, 2011). "CDC25A shows approximately 30% deletion among ovarian tumor samples with unvarying methylation levels and expression correlation with deletion." (PMID 22174824, 2011).
Overgrowth (1 paper, 2024). Excessive postnatal growth which may comprise increased weight, increased length, and/or increased head circumference. "Cyclosporine-A-induced gingival overgrowth may be alleviated by inducing cell cycle arrest through the downregulation of CDC25A, CDK4/6, CYCLIN D, and pRB, along with the enhancement of SMAD3, SMAD4, and RB in gingival fibroblasts." (PMID 39727652, 2024).
paraganglioma (1 paper, 2025). A benign or malignant neoplasm arising from paraganglia located along the sympathetic or parasympathetic nerves. "Distinct from CDC25A and CDC25B, the methylation level of CDC25C decreased in most tumor tissues, including KIRP, LUSC, PRAD, UCEC, LIHC, BLCA, LUAD, and pheochromocytoma and paraganglioma (PCPG)." (PMID 40216745, 2025).
periodontitis (1 paper, 2024). An acute or chronic inflammatory process that affects the tissues that surround and support the teeth. "For instance, PRF serum up-regulated genes such as CCNE2 and CDC25A linked to the cell cycle, as well as DKK1, a WNT-signaling antagonist with a potential impact on inflammatory osteolysis in rheumatoid arthritis and in periodontitis." (PMID 39120336, 2024).